EMX2OS (EMX2 opposite strand/antisense RNA)
Synonyms: NCRNA00045; EMX2-AS1
Gene: Long non-coding RNA gene on chromosome 10 (117,473,213 to 117,545,068, reverse strand). Ensembl gene ENSG00000229847.
Diseases named in the same sentence as EMX2OS in open-access papers:
EMX2OS is named in the same sentence as 33 diseases in open-access papers, as found by Europe PMC text mining. Sharing a sentence is not in itself a finding about the gene and the disease. The quoted sentences say what the papers report.
ovarian carcinoma (11 papers, 2020 to 2023). A malignant neoplasm originating from the surface ovarian epithelium. "EMX2OS plays an important role in the prognosis of gastric cancer and regulates proliferation and invasion of ovarian cancer through the miR-654-3p/AKT3/PD-L1 regulatory axis." (PMID 37600792, 2023). "EMX2OS was shown to promote proliferation, invasion and stemness in ovarian cancer cells, but down-regulation of EMX2OS is correlated with a shorter recurrence-free survival in classic papillary thyroid cancer." (PMID 35205253, 2022). "For instance, overexpression of EMX2OS was reported in gastric cancer and ovarian cancer resulting in the enhancement of proliferation and invasion of cancer cells." (PMID 34703931, 2021). "Furthermore, the abnormal expression and functional role of EMX2OS were also gradually disclosed in various human cancers, including prostate cancer, ovarian cancer, and papillary thyroid cancer." (PMID 37069939, 2023). "We have found that EMX2OS, which has been expressed in ovarian cancer, may inhibit tumor development and development by acting on PD-L1 (procedural cell death protein 1) through the EMX2OS/miR-654/AKT3 axis." (PMID 35662687, 2022). "The lncRNA EMX2OS can bind directly to miR654 and inhibit its expression, leading to the upregulation of PD-L1 and the promotion of proliferation, invasion, and spheroid formation in ovarian cancer cells." (PMID 35266439, 2022). "The lncRNA EMX2OS has been reported to affect the proliferation and invasion of ovarian cancer cells by sponging miR-654-3p to regulate AKT3 and the downregulation of EMX2OS results in a poor prognosis of patients with kidney renal clear cell carcinoma." (PMID 35675043, 2022).
papillary thyroid cancer (8 papers, 2018 to 2025). "Previously, it was reported that EMX2OS predicted the recurrence-free survival of papillary thyroid cancer and correlated with the poor prognosis of kidney renal clear cell carcinoma." (PMID 37069939, 2023). "The downregulation of lncRNA EMX2OS might independently predict shorter recurrence-free survival of classical papillary thyroid cancer." (PMID 31001325, 2019). "In this study, using data from the Cancer Genome Atlas-Thyroid Cancer (TCGA-THCA), we aimed to examine the expression profile of EMX2 and its antisense transcript EMX2OS in papillary thyroid cancer (PTC), their prognostic value and potential regulatory networks." (PMID 30576338, 2018). "In a study by Gu, reduced expression of EMX2OS was identified and suggested as a potential prognostic biomarker for poor recurrence-free survival (RFS) in classical papillary thyroid carcinoma (PTC)." (PMID 41150811, 2025). "EMX2OS, a tumor suppressor in several cancers, is strongly downregulated in follicular and papillary thyroid cancer, but also has not been intensely studied in the glioblastoma context." (PMID 40004468, 2025).
gastric cancer (5 papers, 2021 to 2025). A primary or metastatic malignant neoplasm involving the stomach. "EMX2OS has shown significant diagnostic and prognostic value in a variety of cancers, such as gastric cancer and renal clear cell carcinoma, where its expression level is significantly correlated with patient grade, stage and cancer status." (PMID 40994527, 2025). "EMX2OS plays a prognosis-associated eRNA role in gastric cancer, which might be a novel therapeutic target in clinical practice." (PMID 34731149, 2021). "miR-653-5p was predicted to be a target of EMX2OS and regulates the progression of breast cancer, prostate cancer, and gastric cancer." (PMID 37069939, 2023). "The dysregulation of EMX2OS was widely noted in a variety of cancer, such as gastric cancer, breast cancer, laryngeal cancer, and cervical cancer." (PMID 37069939, 2023). "Plus, a previous study reported that lncRNA EMX2OS was significantly upregulated in gastric cancer tissues compared with normal tissues, which is consistent with our results." (PMID 34731149, 2021). "The results demonstrated that higher expression levels of LINC01714, ZNF192P1, AC079760.2, LINC01645, EMX2OS, and AC114489.2 were significantly associated with the poor survival of gastric cancer patients." (PMID 34731149, 2021). "A total of 63 prognostic-associated eRNAs in gastric cancer were identified, the top 6 eRNAs were LINC01714, ZNF192P1, AC079760.2, LINC01645, EMX2OS, and AC114489.2." (PMID 34731149, 2021). "In this study, the top key eRNA candidate in gastric cancer is EMX2OS." (PMID 34731149, 2021). "The results suggested that eRNA EMX2OS is a prognosis-related gene for gastric cancer." (PMID 34731149, 2021). "Also, EMX2OS has shown the most significant impact on overall survival in gastric cancer among all identified eRNAs." (PMID 34731149, 2021). "eRNA EMX2OS may be a therapeutic target for patients with gastric cancer." (PMID 34731149, 2021). "However, the effects and mechanisms of EMX2OS in gastric cancer remain largely unknown." (PMID 34731149, 2021).
prostate carcinoma (4 papers, 2021 to 2023). A carcinoma that arises from epithelial cells of the prostate gland. "Another study reported that EMX2OS acted as a synergistic role in regulating the proliferation and migration of prostate cancer cells." (PMID 36213821, 2022). "have recently revealed the negative regulatory role of EMX2OS in the proliferation and invasion of prostate cancer cells." (PMID 34703931, 2021). "EMX2OS is a key metabolism-related enhancer RNA in KIRC with a favorable impact on survival and EMX2OS is regulated by TCF12 transcription and co-regulates the proliferation, migration and invasion of prostate cancer cells with FUS protein by activating cGMP-PKG pathway." (PMID 33517850, 2021).
laryngeal carcinoma (3 papers, 2020 to 2023). Carcinoma that arises from the laryngeal epithelium. "have introduced EMX2OS as a novel diagnostic biomarker for recurrent laryngeal cancer and recurrence-free survival time of patients." (PMID 34703931, 2021).
thyroid cancer (3 papers, 2018 to 2021). "Furthermore, LIFR-AS1 regulates invasion and metastasis in thyroid cancers, while the downregulation of EMX2OS is associated with poor patient prognosis in clear cell carcinoma of the kidney." (PMID 35201514, 2021). "In this study, using data from the Cancer Genome Atlas-Thyroid Cancer (TCGA-THCA), we examined the expression profile of EMX2 and EMX2OS in PTC, their prognostic value and potential regulatory networks." (PMID 30576338, 2018).
adrenocortical carcinoma (2 papers, 2020 to 2021). "The pan-cancer analysis demonstrated that EMX2OS was associated with poor survival outcomes in adrenocortical carcinoma, cervical squamous cell carcinoma and endocervical adenocarcinoma, kidney renal clear cell carcinoma, stomach adenocarcinoma, and uveal melanoma." (PMID 34731149, 2021). "EMX2OS also played a prognostic role in adrenocortical carcinoma, cervical squamous cell carcinoma and endocervical adenocarcinoma, stomach adenocarcinoma, and uveal melanoma." (PMID 33234727, 2020). "Finally, we identified that eRNA EMX2OS also plays important roles in 5 tumors, including adrenocortical carcinoma, cervical squamous cell carcinoma and endocervical adenocarcinoma, kidney renal clear cell carcinoma, stomach adenocarcinoma, and uveal melanoma." (PMID 34731149, 2021).
breast carcinoma (2 papers, 2021 to 2023). "The small sample size in our project or the distinctive role of EMX2OS in breast cancer versus other cancers can be possible reasons for this contrary result." (PMID 34703931, 2021). "EMX2OS and FOXN3-AS1 were chosen from a list of 30 lncRNAs that were located near breast cancer-associated SNPs." (PMID 34703931, 2021). "In this study, we selected two lncRNAs (EMX2OS and FOXN3-AS1) that are resided near the GWAS-identified SNPs for breast cancer (rs2901157 and rs141061110)." (PMID 34703931, 2021). "In the present study we aimed to quantify expression level of two lncRNAs (EMX2OS and FOXN3-AS1) resided near the GWAS-identified SNPs for breast cancer (rs2901157 and rs141061110) in the breast cancer and normal adjacent tissues." (PMID 34703931, 2021). "In the present investigation, we aimed to quantify the expression level of EMX2OS and FOXN3-AS1 in 44 breast cancer samples and normal adjacent tissues (ANCTs)." (PMID 34703931, 2021).
cervical cancer (2 papers, 2021 to 2023). A primary or metastatic malignant neoplasm involving the cervix. "Previous studies had shown that four immune-related lncRNAs including BZRAP1-AS1, EMX2OS, ZNF667-AS1, and CTC-429P9.1, significantly correlated with immune cell infiltration and had important prognostic value for cervical cancer patients." (PMID 33959151, 2021).
chronic fatigue syndrome (2 papers, 2019 to 2021). "LncRNA EMX2OS was also identified as associated with myalgic encephalomyelitis/chronic fatigue syndrome." (PMID 31001325, 2019).
lymph node metastasis (2 papers, 2020 to 2023). "EMX2OS downregulation was significantly associated with unfavorable clinicopathological features such as higher histological grade, larger tumor size, lymph node metastasis, distant metastasis, and advanced AJCC stage." (PMID 33234727, 2020). "Alerted expression of EMX2OS was revealed to be related to LUAD development indicated by its close relationship with patients’ lymph node metastasis, poor differentiation, and advanced TNM stage." (PMID 37069939, 2023). "Meanwhile, EMX2OS was identified as an independent prognostic factor (HR = 3.007, 95% CI = 1.090–8.297) together with the TNM stage (HR = 2.510, 95% CI = 1.071–5.883) and lymph node metastasis (HR = 2.358, 95% CI = 1.055–5.269)." (PMID 37069939, 2023).
autoimmune disease (1 paper, 2018). A disorder resulting from loss of function or tissue destruction of an organ or multiple organs, arising from humoral or cellular immune responses of the individual to their own tissue constituents. "Further comparing the PBMC expression signature of NTT, MIAT, and EMX2OS in ME/CFS with patients suffering from chronic fatigue due to autoimmune diseases or cancer is important to assess the lncRNA test specificity in diagnosing ME/CFS." (PMID 30119681, 2018).
breast invasive carcinoma (1 paper, 2020). "Interestingly, EMX2OS expression was significantly lower in many other types of cancers, including breast invasive carcinoma, colon adenocarcinoma, kidney chromophobe, and liver hepatocellular carcinoma, than in normal tissues." (PMID 33234727, 2020).
cholangiocarcinoma (1 paper, 2020). A carcinoma that arises from the intrahepatic biliary tree (intrahepatic cholangiocarcinoma) or from the junction, or adjacent to the junction, of the right and left hepatic ducts (hilar cholangiocarcinoma). "Of interest, EMX2OS and EMX2 showed significant correlations in all cancers, except cholangiocarcinoma." (PMID 33234727, 2020).
deafness (1 paper, 2024). An inherited or acquired condition characterized by the complete loss of the ability to hear from one or both ears. "LncRNAs, such as Lockd, Dlx1as, Emx2os, and Soxot, are of interest because they are located in unresolved deafness-associated loci." (PMID 38826689, 2024).
endometrial tumors (1 paper, 2010). "Emx2OS expression has been studied by in situ hybridisation in the uro-genital system: like Emx2-mRNA, Emx2OS-ncRNA is abundant in normal postmenopausal endometrium, reduced in premenopausal endometrium, absent/reduced in many primary endometrial tumors." (PMID 20066053, 2010).
invasive ductal breast carcinoma (1 paper, 2021). The most common type of invasive breast carcinoma, accounting for approximately 70% of breast carcinomas. "In contrast with the previously reported studies in various cancers and location of EMX2OS in rs2901157 locus, we could not find different expression levels for EMX2OS in invasive ductal breast carcinoma samples versus ANCTs." (PMID 34703931, 2021).
lung adenocarcinoma (1 paper, 2023). A carcinoma that arises from the lung and is characterized by the presence of malignant glandular epithelial cells. "This study aimed to evaluate the significance of EMX2OS in lung adenocarcinoma (LUAD) prognosis and development and its potential molecular mechanism." (PMID 37069939, 2023).
lung carcinoma (1 paper, 2023). "In this study, 117 LUAD patients were enrolled and decreased expression of EMX2OS was found in tumor versus normal tissues consistent with previous studies revealing its downregulation in lung cancer." (PMID 37069939, 2023).
lung diseases (1 paper, 2025). "This study further clarified the role of EMX2OS in the regulation of cell fate in the pathological development of ALI, and complemented the mechanistic studies of lncRNAs affecting cell viability and ferroptosis in lung diseases." (PMID 40994527, 2025).
melanoma (1 paper, 2021). A malignant, usually aggressive tumor composed of atypical, neoplastic melanocytes. "We observed a downregulation of EMX2OS in several melanoma cell lines, compared with PM." (PMID 34218270, 2021). "Moreover, analysis of LMC patient data demonstrated an inverse relationship between EMX2OS expression and tumour thickness, mitotic rate, and survival, suggesting that this lncRNA may function as a tumour suppressor in melanoma." (PMID 34218270, 2021). "The SFPQ-enriched lncRNA transcripts most specific to PM were EMX2OS and FENDRR, the latter reported to function as a tumour suppressor in most cancers, including melanoma." (PMID 34218270, 2021).
Neonatal sepsis (1 paper, 2025). Systemic inflammatory response to infection in newborn babies. "Based on this, future studies can develop small molecule inhibitors or RNA interference technology specifically targeting EMX2OS/miR-654-3p/AKT3 axis, which may provide a new treatment strategy for improving the prognosis of neonatal sepsis." (PMID 40994527, 2025).
Sepsis (1 paper, 2025). Sepsis is defined as life-threatening organ dysfunction caused by a dysregulated host response to infection. "The expression level of EMX2OS in the serum of neonates with sepsis was significantly higher than that of healthy neonates (P < 0.001)." (PMID 40994527, 2025).
tumor (18 papers, 2018 to 2025). "First of all, the significance of EMX2OS in prognosis prediction has been demonstrated in this study, and the potential molecular mechanism underlying the function of EMX2OS was disclosed, indicating the importance of lncRNAs in tumor-related research." (PMID 37069939, 2023). "Although the tumor suppressor role of EMX2 might help to explain the association between EMX2/EMX2OS expression and better RFS in classical PTC, the exact regulatory effect of EMX2/EMX2OS in this variant have been not explored." (PMID 30576338, 2018). "However, it is interesting to note that the most PM-specific SFPQ-lncRNA interactors included genes associated with tumour suppressor function, such as EMX2OS and FENDRR, whereas the most A2058-specific SFPQ-lncRNA interactors comprise genes widely reported as oncogenic, such as LINC00511." (PMID 34218270, 2021). "Taken together, downregulated EMX2OS in LUAD was identified as an independent prognostic indicator and associated with tumor progression." (PMID 37069939, 2023). "Consistent with the dysregulation of EMX2OS and miR-653-5p in tumor tissues, the downregulation of EMX2OS and the upregulation of miR-653-5p were also found in the LUAD cells compared with normal cells (P < 0.01, P < 0.001)." (PMID 37069939, 2023). "In mechanism, the interaction between EMX2OS and miR-653-5p was assessed by the dual-luciferase reporter assay, and the regulatory effect of miR-653-5p on EMX2OS tumor suppressor role was also estimated." (PMID 37069939, 2023). "EMX2OS was previously reported as upregulated in OC tissues and cell lines, enhancing proliferation, invasion, and sphere formation in vitro and tumor growth in vivo." (PMID 35406435, 2022). "The Emx2os molecule is an antisense transcript of homeobox protein Emx2os, a known transcription factor with tumor suppressor abilities, e.g., in LSCC." (PMID 34204634, 2021). "In contrast, ectopic expression of PD-L1 can eliminate the tumor suppressive effect of downregulation of EMX2OS and AKT3 or overexpression of miR-654 in OC cells." (PMID 34496886, 2021). "In terms of tumor grade, eRNA EMX2OS expression is higher in the G3 grade than those in the G2 grade." (PMID 34731149, 2021). "Based on the expression data of 535 KIRC samples and 72 normal kidney samples, we found that EMX2OS expression was significantly lower in tumor tissues than in normal tissues (p < 0.001)." (PMID 33234727, 2020). "Compared with the matched tumor-free samples, EMX2OS and EMX2 expression levels were downregulated in 91.7% (11 of 12) and 83.3% (10 of 12) of KIRC samples, respectively." (PMID 33234727, 2020). "These analyses showed that the metabolism of several energy-involved substances, such as fatty acid and pyruvate, were enriched, which suggests that EMX2OS influences the energy metabolism of the tumor." (PMID 33234727, 2020). "On this basis, we built the relevant ceRNA network and found that EMX2OS might have an important function in the ccRCC tumor microenvironment through the EMX2OS/hsa‐miR‐31‐5P/TLN2 axis." (PMID 38808948, 2024). "The EMX2OS/hsa‐miR‐31‐5P/TLN2 axis might yield functional impact on tumor microenvironment in ccRCC and may represent a novel therapeutic target for ccRCC." (PMID 38808948, 2024). "Additionally, reduced EMX2OS was negatively correlated with the increased miR-653-5p in tumor tissues (r = −0.773, P < 0.001)." (PMID 37069939, 2023). "Additionally, EMX2OS negatively regulates miR-653-5p, and miR-653-5p mediated the tumor inhibitory effect of EMX2OS on LUAD cells." (PMID 37069939, 2023). "Although rarely reported, we speculate that EMX2OS also serves as a tumor suppressor because of its strong co-expression relationship with EMX2." (PMID 33234727, 2020). "All results were consistent and suggested that EMX2OS serves as a tumor suppressor in KIRC." (PMID 33234727, 2020). "Thus, BZRAP1-AS1 and EMX2OS may play a dual role in cancer and directly or indirectly regulate tumor immunology." (PMID 33274204, 2020).
tumor (continued). "lncRNAs such as DIO3OS, EMX2OS, KCNQ1DN, KCNQ1OT1, LOH12CR2, and RFPL1S have been shown to associate with a negative gene signature, which links lncRNA to tumor suppression mechanisms." (PMID 41300873, 2025). "In the case of EMX2OS, despite previous studies in other malignancies, we could not find a significant difference in its expression between tumor and control samples." (PMID 34703931, 2021).